IL6 (interleukin 6)
Diseases named in the same sentence as IL6 in open-access papers (continued):
Sharing a sentence is not in itself a finding about the gene and the disease.
bladder cancer (continued). "Moreover, decreased expression of IL-6 increases MDSCs accumulation, thus providing the immunosuppressive microenvironment for the development of bladder cancer." (PMID 28418913, 2017). "Accordingly, we found that IL-6 expression is also upregulated in bladder cancer cells." (PMID 27499248, 2016). "Therefore, we conclude that in bladder cancer cells, up-regulation of IL-6 induces SLD5 expression to promote acute proliferation of cancer cells." (PMID 27499248, 2016). "Although the function and expression of NDRG family genes with regard to bladder carcinoma cells remain poorly understood, our previous report has indicated that NDRG1 is upregulated by interleukin 6, which blocks cell proliferation and invasion in bladder carcinoma cells." (PMID 26249737, 2015). "Therefore, the present study was performed to highlight the role of IL-6 in improving treatment and determining prognosis of bladder cancer." (PMID 23637926, 2013). "The dysregulation of the EMT and the altered MASPIN, NDRG1, and KAI1 gene expression induced by IL6 may lead to the modulation of tumorigenesis in bladder carcinoma cells." (PMID 23762858, 2013). "The findings strongly underscore the contribution of IL-6 to the prognosis in bladder cancer." (PMID 23637926, 2013). "The elucidation of whether IL6 directly or indirectly affects EMT markers in bladder carcinoma cells by inducing of MASPIN and NDRG1 warrants further investigation." (PMID 23762858, 2013). "Because IL6 plays a fundamental role in supporting the systemic host response to tissue injury, the higher levels of IL6 in bladder cancer patients may be the results of a complex systemic immune response mediated by peripheral blood mononuclear cells." (PMID 23762858, 2013). "Although there is evidence suggesting that IL-6 may be a critical factor in various malignancies, its role in bladder cancer remains unclear." (PMID 23637926, 2013). "Additionally, IL-6 silencing vector significantly attenuated the invasive capacity of bladder cancer cells as demonstrated using migration scratch assays and invasion assay in vitro." (PMID 23637926, 2013). "The data support the emerging hypothesis that IL-6 is a clinically significant prognostic predictor and may represent a suitable target for bladder cancer treatment." (PMID 23637926, 2013). "The mechanism by which IL6 affects the tumorigenicity of these bladder carcinoma cell lines remains unclear." (PMID 23762858, 2013). "Our findings suggest the possible functions of IL6 in human bladder carcinoma cells." (PMID 23762858, 2013). "We outlined the main signaling pathways that are thought to link IL-6 to bladder cancer." (PMID 23637926, 2013). "In conclusion, our findings showed that IL-6 could be a significant predictor for clinical stage and prognosis of bladder cancer." (PMID 23637926, 2013). "However, a critical role for bladder cancer cells, via the production of specific cytokines such as IL-6, IL-8, and IL-17, in promoting tumor growth has recently been demonstrated." (PMID 22962576, 2012). "IL-6 and IL-6sR were related to tumor stage and metastasis, and previous research has demonstrated that pre-operative IL-6 and IL-6sR levels could be related to a poorer prognosis for bladder cancers receiving radical cystectomy." (PMID 37298699, 2023). "Moreover, blocking IL6 expression attenuated invasive capability of bladder cancer cells." (PMID 33244139, 2020). "Here, we investigated whether HMGN5 participates in IL-6-Hsp27-induced EMT in bladder cancer." (PMID 32315283, 2020). "Herein, we show how one of the mediators of such an interaction, namely IL-6, mainly secreted by CAFs, can support tumor progression and how it can be antagonized by a neutralizing antibody to its receptor, which significantly reduces proliferation, migration and invasion in bladder cancer cells." (PMID 30744595, 2019).
bladder cancer (continued). "Thus, downregulation of IL-6 by siRNA could suppress Sld5 expression in T24 bladder cancer cell line and injection of miR-370 could inhibit tumor growth in the mouse xenograft experiment." (PMID 29651420, 2018). "Therefore, bladder cancer could be tested for anti-IL-6 therapies to find whether tumor growth could be suppressed by preventing the autocrine loop of cancer cells which leads to Sld5 downregulation." (PMID 29651420, 2018). "Therefore, targeting the IL-6 signaling may be a promising strategy for the treatment of bladder cancer." (PMID 28418913, 2017). "Therefore, it is suggested that activation of AKT might be responsible to the increased DNMT1 in IL-6-positive bladder cancers." (PMID 23637926, 2013). "In addition to IL-6, several cytokines were reported to be important in studies of bladder cancer." (PMID 23637926, 2013). "However, the biological mechanisms that are affected by the expression of interleukin-6 in bladder cancer cells remain unclear." (PMID 23762858, 2013). "On one hand, EP300 loss-of-function relieves its inhibition on IL-1α signaling, activating the IL-6/JAK/STAT3 pathway and driving bladder cancer." (PMID 40375990, 2025). "For IL-6 and TNF-α, the simultaneous, significant elevation of these two proinflammatory cytokines implies that bladder cancer exists within an environment of persistent inflammation." (PMID 41614883, 2025). "Their findings demonstrate that CAFs are a primary source of IL-6 in the TIME, while bladder cancer cells express the IL-6 receptor (IL-6R)." (PMID 40141426, 2025). "In our study, we aimed to investigate the relationship between miRNA-21, miRNA-155, miRNA-34a, IL-6, TGF-β, and TNF-α expression levels and serum trace element levels in the development and progression of bladder cancer." (PMID 41614883, 2025). "One study showed that low SMARCB1 expression promoted Bladder cancer growth by activating STAT3; therefore, targeting the IL6/JAK/STAT3 pathway is a potential treatment for SMARCB1-deficient tumors." (PMID 40115023, 2025). "Our previously published studies demonstrated that activation of the IL6/STAT3 pathway plays a major role in the induction of cell motility, especially in MØs and bladder cancer cells." (PMID 40807456, 2025). "Hua Wei reported that IL6/IL6R/STAT3 axis is critical for the maintain of the stem-like properties, and blockage of IL6R inhibit the invasion, migration and tumorigenicity of bladder cancer CSCs." (PMID 38462600, 2024). "From the human data, the urine of bladder cancer patients had significantly upregulated levels of CCL2, IL-6, CXCL10, IL-1b, IFN-g, TGF-b, and IL-8 in comparison to the healthy donors." (PMID 37901214, 2023). "In comparison to healthy donors, CCL2, IL-6, CXCL10, IL-1b, IFN-g, TGF-b, and IL-8 were enriched within the urine of bladder cancer patients." (PMID 37901214, 2023). "In human bladder cancer cells, suppression of MMP-2, MMP-9 and IL-6 expression, as well as induction of mesenchymal-to-epithelial transition (MET were found in the presence of DEX." (PMID 36980530, 2023). "The levels of IL-6, IL-10, CCL2 were significantly decreased in both two bladder cancer cell lines, and Other transcription factors are uncertain in cell lines." (PMID 35769470, 2022). "In this investigation, we found that silencing IQGAP2 increased IL-6 and CCL2 levels in bladder cancer cells, whereas the overexpression of IQGAP2 lowered IL-6, IL-8, and CCL2 levels." (PMID 36362301, 2022). "In this work, we reported that cisplatin treatment of bladder cancer cells produced specific immune effects, which mainly included the secretion of important cytokines (such as interferon type I cytokines, IFN-β, and IL6)." (PMID 36230972, 2022). "Therefore, targeting IL-6 may be a promising strategy for treating bladder cancer." (PMID 34884178, 2021). "IL-6-induced the upregulation of DNA-methyltransferase (DNMT) inhibits miR-370, leading to high GINS4 expression and tumor growth in bladder cancer." (PMID 33842367, 2021).
bladder cancer (continued). "Upon IL-6 stimulation, HMGN5/Hsp27 modulates bladder cancer EMT and bladder cancer cell invasion via the STAT3/Twist signaling pathway." (PMID 32315283, 2020). "HMGN5 interacts with Hsp27 to modulate IL-6-independent- or IL-6-dependent EMT and cell invasion in bladder cancer cells." (PMID 32315283, 2020). "Next, the dynamic effects of HMGN5 and Hsp27 on IL-6-independent- and IL-6-dependent EMT and invasion in bladder cancer cells were evaluated." (PMID 32315283, 2020). "Proinflammatory cytokines, such as IL-6, IL-8, and TNF-α, play critical roles in the pathogenesis of bladder cancer." (PMID 32315283, 2020). "We measured the levels of several cytokines (IL-6, IL-12, and IFN-γ) in the 2D and 3D bladder cancer cell models after BCG treatment." (PMID 31639124, 2019). "However, the association between CAFs and IL-6 secretion in bladder cancer has not been shown." (PMID 30744595, 2019). "Our current study further demonstrated that miR-153's anti-tumor activity in bladder cancer cells was mediated by targeting IDO1, which in turn inactivated the IL6/STAT3/VEGF signaling pathway." (PMID 31355138, 2019). "We analyzed IL6 and ACTA2 expression in the publicly available TCGA and GSE13507 gene expression profiling datasets of human bladder cancer samples." (PMID 30744595, 2019). "For these analyses, bladder cancer patients were stratified based on low and high quartiles of ACTA2/IL6 co-expression levels in tumors." (PMID 30744595, 2019). "Corticosterone and prednisone were also shown to reduce the expression levels of MMP-9, IL-6, and VEGF genes in bladder cancer cells." (PMID 30518063, 2018). "As a result of inducing transactivation or transrepression of GR by dexamethasone, up-regulation of FKPB51 and GILZ or down-regulation of NF-κB and AP-1 as well as MMP-2, MMP-9, IL-6, and VEGF, respectively, has been documented in bladder cancer cells." (PMID 30518063, 2018). "The results indicate that the increased expression of HO-1 in bladder cancer is paralleled by changes in the expression of other potentially interacting genes, like Nrf2, HIF-1α, HIF-2α, IL-6, IL-8, and VEGF." (PMID 26927195, 2016). "Moreover, targeting IL-6 may be a promising strategy for treating bladder cancer." (PMID 23637926, 2013). "The human bladder cancer cell lines HT1376 and HT1197 were selected for cell and animal experiments, in which biological changes after experimental manipulation of IL-6 were explored, including tumor behavior and related signaling in bladder cancer." (PMID 23637926, 2013). "Using a human bladder carcinoma cell line, we observed that WT GBS induced significantly more transcription of interleukin (IL)-6, IL-8, and, to a lesser extent, IL-1α, than medium alone or the ΔcylE deletion mutant." (PMID 23505569, 2013). "We found there was a significant correlation between positive staining for IL-6 and DNMT1 on IHC staining of bladder cancer specimens." (PMID 23637926, 2013). "However, the mechanisms by which IL6 affects human bladder carcinoma cells remain unclear." (PMID 23762858, 2013). "The effects of IL6 on the dysregulation of EMT markers and the expressions of MASPIN, NDRG1, and KAI1 genes in bladder carcinoma cells were examined." (PMID 23762858, 2013). "The incubation of NF-κB, which is a transcriptional factor for many cytokines, including the IL-6 induced by GLe on HUC-PC cells, was shown to bear antitumor effects in other bladder cancer cells." (PMID 22969822, 2012). "Among the cytokines released by BCG, attention has been paid to IL-6 because its urinary levels are correlated with symptom scores in cystitis and are reduced by BCG therapy in bladder cancer." (PMID 17506885, 2007). "Therefore, in this study, we aimed to investigate the relationship between miRNA-21, miRNA-155, miRNA-34a, IL-6, TGF-β, and TNF-α proinflammatory cytokines, and serum iron, copper, and zinc levels with the early diagnosis and progression of bladder cancer." (PMID 41614883, 2025).
bladder cancer (continued). "Clinical trials investigating targeted approaches, such as IL-6 signaling inhibition in bladder cancer, are still lacking." (PMID 38542078, 2024). "The correlation between Cr and Cd with the expression of Bax, IL-6, AKT, and P38 may indicate a carcinogenic role of these metals on progression of bladder cancer." (PMID 38072891, 2024). "Based on these results, we may speculate that loss-of-expression in SPOP might also stabilize PD-L1 protein in bladder cancer cells and induce immune escape via TAMs, beyond the STAT3/CCL2/IL-6 axis." (PMID 39479456, 2024). "The level of IL-6, AKT and P38 in bladder cancer tissues specimens were examined using RT-PCR." (PMID 38072891, 2024). "CAFs express the IL-6 cytokine, and its receptor IL-6R was found in RT4 bladder cancer cells." (PMID 37880682, 2023). "Importantly, inhibition of CAFs-secreted IL-6 by neutralizing antibodies significantly reversed the IL-6-induced EMT phenotype, suggesting that this cytokine is essential for CAF-induced EMT in human bladder cancer progression." (PMID 37880682, 2023). "Notably, the present study first identified HME as a potent blocker for STAT3 signaling in bladder cancer cells, as HME markedly inhibited both constitutive and IL-6-inducible STAT3 activation." (PMID 36613579, 2022). "Moreover, reducing the catabolism of tryptophan suppresses IL-6/STAT3/VEGF signaling pathway and attenuates angiogenesis in bladder cancer." (PMID 36559245, 2022). "HMGN5 silencing attenuated IL-6-induced bladder cancer EMT and bladder cancer cell invasion." (PMID 32315283, 2020). "We further investigated the relationship between IL6 and UBC9 in bladder cancer samples." (PMID 33244139, 2020). "Moreover, we found that silencing LINC00482 inhibited inflammation and angiogenesis in bladder cancer through the down-regulation of MMP-15 by targeting FOXA1, along with decreased levels of TNF-α, IL-1β, and IL-6 as well as the expression of VEGF and NF-κB." (PMID 33323547, 2020). "Importantly, inhibition of CAFs-secreted IL-6 by neutralizing antibody significantly reversed the IL-6-induced EMT phenotype, suggesting that this cytokine is necessary for CAF-induced EMT in the progression of human bladder cancer." (PMID 30744595, 2019). "IL-6 is overexpressed in bladder cancer tissues compared to non-malignant tissues at both mRNA and protein levels and elevated IL-6 levels correlated with higher clinical stage, higher recurrence rate after curative treatment, and reduced survival rate." (PMID 30744595, 2019). "Although there is evidence suggesting that CAFs and IL-6 may be a critical factor in metastatic spreading, their role in EMT of bladder cancer cells remains unclear." (PMID 30744595, 2019). "We found that, IL-6 expression was significantly suppressed in the experimental groups compared to the control groups, while phosphorylated STAT3 and VEGF were also significantly decreased in miR-153-overexpressing or IDO1 knocked down bladder cancer cells." (PMID 31355138, 2019). "In contrast, growth of the other two bladder cancer cell lines that we studied was not significantly affected by IL-17, despite eliciting a response by increased production of IL-6 and IL-8." (PMID 28931051, 2017). "Here, we also found that IL-6 and DNMT1 expression were correlated in bladder cancer." (PMID 27499248, 2016). "Our results suggest that the effects of interleukin-6 on the regulation of epithelial-mesenchymal transitions and the expressions of the MASPIN, NDRG1, and KAI1 genes attribute to the modulation of tumorigenesis in human bladder carcinoma cells." (PMID 23762858, 2013). "The data revealed that IL-6 was overexpressed in the bladder cancer specimens compared with non-malignant tissues at both mRNA and protein levels." (PMID 23637926, 2013). "Urinary IL-6 levels were significantly elevated in patients with T3 –T4 local-advanced bladder cancers (250±27 pg/mL) compared to those in patients with ≤T2 bladder cancer or non-malignant disease (P = 0.01)." (PMID 23637926, 2013).
bladder cancer (continued). "The relationship between IL-6/STAT3 signaling and DNMT1 in bladder cancer was further examined to see whether regulation of IL-6/STAT3 signaling results in changes of DNMT1 expression." (PMID 23637926, 2013). "IL1b, IL6, GMCSF, MCSF, GCSF, and TNFα are expressed in a human bladder carcinoma cell line." (PMID 22013484, 2011). "The positive significant correlations between miRNA-34a and IL-6 and TGF-β in patients with bladder cancer could be due to the complexity of the cancer microenvironment, the structure of molecular signaling networks, or the special functions in the binding of miRNAs." (PMID 41614883, 2025). "Similarly, a study of 85 patients with muscle-invasive bladder cancer revealed that IL-6 was expressed at higher levels in bladder cancer compared to non-malignant tissues." (PMID 40141426, 2025). "Research has demonstrated that inflammatory cytokines (e.g., IL-6, TNF-α) can inhibit erythrocyte maturation, leading to increased RDW, while simultaneously activating oncogenic pathways such as STAT3, promoting tumorigenesis, immune evasion, and driving bladder cancer progression." (PMID 41561745, 2025). "Therefore, we hypothesize that elevated WDHD1 expression may impact immune cells like CD8+ T cells and secrete IL-6 and TGF-β, which may result in people with bladder cancer having a dismal prognosis." (PMID 38980253, 2024). "Therefore, the aim of this study was to determine whether concentrations of heavy metals such as Pb, Cr, Hg, and Cd have any effect on oxidative stress and expression of some genes Bcl-2, Bax, IL-6, AKT, and P38 genes in bladder cancer patients." (PMID 38072891, 2024). "Notably, cisplatin treatment significantly promoted the expression of these cytokines in GFP-knockdown but not Hotair-knockdown cells, indicating that knockdown of Hotair abolished cisplatin-induced upregulation of IL-6, TNF-α, and IL-1β in mouse bladder cancer cells." (PMID 36471329, 2022). "Consistent with previous studies, we also found that AnxA2 knockdown significantly inhibited bladder cancer cell proliferation, migration, and invasion, along with remarkably decreased expression of proangiogenic proteins such as PDGF-BB, ANGPT1, ANGPT2, Tie-2, bFGF, GRO, IL-6, IL-8, and MMP-9." (PMID 36428758, 2022). "In addition, the downregulation of AnxA2 cells significantly inhibited the proliferation, migration, and invasion in bladder cancer along with the reduction in proangiogenic factors and cytokines such as PDGF-BB, ANGPT1, ANGPT2, Tie-2, bFGF, GRO, IL-6, IL-8, and MMP-9." (PMID 36428758, 2022). "Furthermore, HME was proved as a blocker for STAT3 activation, evidenced by the findings that HME inhibits both constitutive and IL-6-induced activation of STAT3, and STAT3 blockage is needed for HME to suppress the viability and clonogenicity of bladder cancer cells." (PMID 36613579, 2022). "Moreover, HMGN5 could modulate IL-6-Hsp27-induced EMT and invasion in bladder cancer cells by regulating STAT3 phosphorylation and STAT3-mediated Twist transcription." (PMID 32315283, 2020). "Thus, we hypothesize that HMGN5 may interact with Hsp27 to affect IL-6-induced EMT and invasion in bladder cancer by modulating STAT3 phosphorylation and STAT3 targeting of the Twist promoter." (PMID 32315283, 2020). "Thus, we speculate that the role of miR-153 in bladder cancer angiogenesis is to target IDO1 expression and regulate IL6/STAT3/VEGF signaling." (PMID 31355138, 2019). "However, an evaluation of the direct effects of IL-6 on human bladder carcinoma cells has not been well defined." (PMID 23762858, 2013). "Bladder cancer specimens expressed substantially higher level of IL-6 than non-malignant tissues." (PMID 23637926, 2013).